TERT (telomerase reverse transcriptase)
Diseases named in the same sentence as TERT in open-access papers (continued):
Sharing a sentence is not in itself a finding about the gene and the disease.
tumor (continued). "Studies have shown that despite ubiquitous telomerase rejuvenation, a continued shortening of telomeres in tumor cells, particularly in presence of the TERT promoter mutations, in the initial stages lead to chromosomal fusions and aneuploidy." (PMID 30026606, 2018). "Tumours with TERTp mutations were consistently reported to express higher levels of TERT mRNA and telomerase activity when compared to those with a wildtype promoter." (PMID 29751586, 2018). "TERT polymorphisms are being addressed as factors with impact on the risk of developing several cancers, with increasing evidence for tumours of the CNS and lung." (PMID 29751586, 2018). "For 1659 of the 2648 cases information on tumour, 1p/19q co-deletion, TERT promoter and IDH mutation status was available." (PMID 29460007, 2018). "The high frequency of TERT promoter mutations in just two nucleotide positions strongly suggests a possible role as drivers, i.e., primary or secondary events in tumor pathogenesis." (PMID 29463038, 2018). "TERT promoter mutation was preferably used over 1p/19q codeletion for molecular subtyping of the tumor according to previous reports that confirmed that this genetic mutation is prognostic." (PMID 30082856, 2018). "TERT, a telomerase reverse transcriptase that maintains telomere ends, is currently the only gene known to be upregulated in several tumor types by a mutation in its promoter." (PMID 29855388, 2018). "The five key variables were MGMT promoter methylation status (MGMT), ADC value (ADC), age, tumor edema (edema), and TERT promoter mutation status (TERT)." (PMID 29984907, 2018). "We chose 3 studies (heterogeneity: Chi2 = 1.03, I2 = 0%, Z = 9.38, P < .01, Fixed efforts model) to do the meta-analysis and found that TERT promoter mutations were relevant to larger tumor size." (PMID 30024548, 2018). "We predicted that patients with high peritumoral edema that was preoperatively detected through MRI imaging and TERT promoter mutations that were postoperatively detected in tumor tissue would have a poorer prognosis and a higher mortality." (PMID 29984907, 2018). "On the other hand, TERT promoter hypermethylation is associated with gene silencing; thus, in the tumor environment, one would expect selection for cells that acquired different mechanisms to protect the TERT promoter from DNA methylation." (PMID 29439385, 2018). "TERT promoter mutations were similarly associated with increased aggressiveness of human cancers, as exemplified by increased tumor recurrence and disease-specific mortality of PTC5 and aggressiveness of melanoma, glioma, and bladder cancer." (PMID 29422527, 2018). "If so, the clonal VHL and TERT driver mutations also seen in this tumor must have preceded the chromothripsis." (PMID 29656891, 2018). "We analyzed TERT promoter hotspot mutations (C228T and C250T) using direct sequencing of DNA from 319 tumor tissues." (PMID 29222734, 2018). "The neoplasia predisposing effect of the risk alleles at the TERT locus (rs72709458; rs2736100; rs2853676) has been overwhelmingly documented." (PMID 30226466, 2018). "Assessment of telomere length from tumor biopsies revealed that TERT promoter-mutated MLSs had significantly fewer shortened telomeres in comparison to TERT wildtype MLSs." (PMID 29463038, 2018). "In consistent with our results, previous studies in PTC cohort have also shown a correlation between TERT promoter mutations and older age at diagnosis, larger tumor size, shorter progression free survival and overall survival." (PMID 28423545, 2017). "Analyses according to tumor stage demonstrated that TERT promoter mutation was seen more frequently in early-stage tumors." (PMID 28854942, 2017).
tumor (continued). "Their study demonstrated the patients harboring both BRAF and TERT mutations had an 8.5 fold greater tumor recurrence rate compared with all PTCs patients with neither mutation." (PMID 28423545, 2017). "The tumor size was significantly greater in the TERT promoter mutation-positive group (32.1 ± 15.7 mm) than in the BRAFV600E alone (19.8 ± 11.4 mm, p < 0.001) or mutation-negative group (22.6 ± 15.3 y, p = 0.001)." (PMID 28150740, 2017). "TERT rearrangements have been described in several neoplasms and are usually associated with increased TERT expression." (PMID 29312603, 2017). "We found Kras mutations also increased the telomerase activities in both Bx-PC3 and Caco-2 cells, suggesting the generality of Kras mutations transactivating TERT expression in tumor cells." (PMID 27329725, 2017). "In NCCHCC, we found that TERT cytoplasmic expression was significantly higher in adjacent tissue and was associated with better tumor differentiation." (PMID 28460432, 2017). "Sequencing of whole tumor genomes holds the promise of revealing functional somatic regulatory mutations, such as those described in the TERT promoter." (PMID 28489852, 2017). "Higher TERT cytoplasmic expression was found in tumor tissues compared to adjacent tissues, and was associated with multiple numbers of tumors and poor prognosis of CCHCCs." (PMID 28460432, 2017). "Recurrent hot spot mutations in TERT promoter (G > A at-124 bp; G > A at −146 bp), have shown to be common events in many tumor types including HCC and to up regulate the expression of telomerases." (PMID 28529542, 2017). "The TERT promoter mutations were linked to many aggressive clinicopathological features such as large tumor size, distant metastasis, advanced stage, and extrathyroidal extension." (PMID 28150740, 2017). "The final analysis confirmed RB1 mutation, TERT copy gain, histotype and tumour stage as independent factors for poor prognosis." (PMID 27873319, 2017). "Expression of the genes encoding WT1, survivin and TERT is used as a prognostic marker, and these TAAs have been characterized as powerful tumor antigens in AML." (PMID 28477011, 2017). "One of the hallmark features of tumor cells, it contributes to their growth advantage and survival, and upregulation of the TERT gene is the major mechanism of telomerase activation in human cancer." (PMID 29100407, 2017). "Of further note, the HVPTC patient with TERT promoter mutation was seventy-six years old with a relatively large tumor size (5cm) and the only HVPTC patients in our cohort who was died of disease (17 months after surgery)." (PMID 28423545, 2017). "Univariate Cox analysis for DFS in cohort #1 showed that the presence of the T349C genotype and TERT gain increased significantly the risk of tumor recurrence with HR of 2.8 and 3.8, respectively." (PMID 29100407, 2017). "In conclusion, we report on the development of a ddPCR assay for the detection of two common TERT promoter mutations in cell lines, tumor tissue and ctDNA." (PMID 29108273, 2017). "Thyroid tumors carrying TERT promoter mutations generally have more aggressive characteristics and higher tumor recurrence and mortality rates." (PMID 29085338, 2017). "The primary and post-treatment autopsy tumor shared a TERT promoter mutation, copy-loss of chromosome 10, and copy-gain of chromosome 7." (PMID 29872714, 2017). "The discovery of the somatic mutations activating TERT promoter in several tumor types adds a new perspective to reevaluate the anti-telomerase strategies." (PMID 28460432, 2017). "We propose a MassARRAY (MS)-based test that can identify 1p/19q codeletion using quantitative SNP genotyping and, simultaneously, characterize hotspot mutations in the IDH1, IDH2, and TERT genes in tumor DNA." (PMID 28915660, 2017).
tumor (continued). "In the stratified meta-analysis by histologic subtype of PTC, we found that the prevalence of TERT promoter mutations was correlated with the degree of tumor aggressiveness." (PMID 26857243, 2016). "The recent study of the genetic evolution of melanocytic lesions demonstrated the TERT promoter mutations are acquired early in tumor evolution, and we would predict other clustered promoter mutations would also be acquired prior to invasive transformation." (PMID 27611953, 2016). "Similar frequencies of TERT mutations have been found in men (49%) and in women (46.8%), as well as in patients with single (48.8%) and multiple (47.7%) tumor sites." (PMID 27276713, 2016). "By direct sequencing of the TERT promoter region, we detected TERT hot spot mutations in 85 (31%) tumor tissues from 276 HCC cases." (PMID 27056898, 2016). "Nevertheless, efforts have been made to demonstrate that TERT is a tumor-associated antigen (TAA) capable of triggering antitumor CD8+ cytotoxic T lymphocyte (CTL) response in multiple tumor types." (PMID 27240403, 2016). "A total of 11 of 80 patients (14%) had PTCs containing TERT promoter mutations: 8 had the C228T mutation and 4 had the C250T mutation (one tumour had both mutations)." (PMID 26667986, 2016). "TERT promoter mutations were detected in 19 (4.4%) of 434 PTCs and were associated with older age (p<0.001), larger tumor size (p = 0.024), and advanced TNM stage(p<0.001)." (PMID 27064992, 2016). "The distribution of mutations among genes is similar to other previous studies on tumor and voided urine, although TERT mutations are lower." (PMID 27611947, 2016). "In four of the 7 cases (57%), the C228T TERT mutation was found in both the paired preneoplastic lesions and the tumor tissue." (PMID 27056898, 2016). "TERT encodes the reverse transcriptase subunit of telomerase required to maintain telomere length during tumor growth." (PMID 27311963, 2016). "In both studies, TERT promoter mutation was associated with larger tumor size, potentially explaining the lower prevalence of TERT promoter mutations among our cases." (PMID 27064992, 2016). "The role of TERT promoter mutations in hepatocarcinogenesis, and the pathogenesis of tumor progression remain to be functionally investigated." (PMID 27661004, 2016). "TERT promoter mutations were associated with older age, larger tumor size, the solid variant of PTC, and more advanced TNM stage in the present study." (PMID 27064992, 2016). "In our study of primary tumours, the percentage of TERT and FGFR3 reads containing mutations varied continuously from undetectable to >50% of the total reads." (PMID 26901314, 2016). "The identification of TERT promoter mutations provides a novel genetic marker to monitor telomerase activation during the process of tumor development." (PMID 27438857, 2016). "Occurrence of more than one mutation for FGFR3 and TERT has been found before and is probably due to either tumor heterogeneity or the presence of multiple tumor clones in the bladder." (PMID 27611947, 2016). "Although most of these transcripts were found to be alternatively spliced variants of Tert which lack functional reverse transcriptase activity, both TERT protein and telomerase enzymatic activity were higher in tumor samples harboring promoter mutations." (PMID 26846696, 2016). "Mutations leading to overexpression of TERT enhance the invasiveness of tumor cells, are more prevalent in older patients with invasive diseases and advanced tumor stages, and are associated with significantly shorter patient survival time." (PMID 26110651, 2015). "Restoration of the C228T mutation to T228C in BCSCs can recover the TERT expression to a basal level and abolish tumor formation." (PMID 26143634, 2015). "In the combined vaccine group, an extraordinary suppression of tumour-associated angiogenesis was observed, confirming that immunization against TERT and VEGFR-2 is a powerful anti-angiogenic strategy." (PMID 26085010, 2015).
tumor (continued). "These suggest that the TERT variants show consistent response to chemotherapy agents in tumor cells and normal cells." (PMID 26020272, 2015). "Two of 92 informative cases (2.2 %) were found to have heterozygous TERT promoter mutations (C228T), and these mutations occurred in a low-risk and a high-risk tumor, respectively." (PMID 26753123, 2015). "Herein, we investigated the presence of TERT-p mutations in 56 patients with histopathologically well-characterized atypical spitzoid neoplasms for whom follow-up information was available." (PMID 26061100, 2015). "Further mechanistic studies in such tumor cells are also challenged by the high frequency of concurrent TERT copy number variations, promoter polymorphisms, and cancer-associated dysregulation of factors implicated in TERT regulation such as MYC." (PMID 26194807, 2015). "Very interestingly, C228T mutation at TERT promoter can efficiently transform normal NBBC into tumor-initiating cells." (PMID 26143634, 2015). "Assignment of IDH-mutated (defined by IDH1 R132 or IDH2 R172 mutations), 1p/19q and TERT promoter mutation (defined by C228T or C250T) status in tumours was determined using conventional sequencing and single-nucleotide polymorphism (SNP) array methods." (PMID 26068201, 2015). "Transient transfection experiments using ectopic TERT Luciferase-reporter constructs suggest that TERT promoter mutations can increase TERT transcription by 1.5–2 fold when assayed in tumor cells." (PMID 26194807, 2015). "Relative mRNA expression analysis was performed on available tumor tissue from 34 patients, four being wild type and thirty four mutated in the TERT promoter." (PMID 26143636, 2015). "Another fusion transcript involving IRX2 and TERT, caused by an interstitial deletion of 5p, was recently reported in a single tumor classified as CCSK." (PMID 26158413, 2015). "In these cells activating TERT promoter mutations will be present in most tumor cells and detected as a frequent and thus early event." (PMID 26194807, 2015). "It was shown that the selective TERT promoter mutational profile was associated with tumor histology and tissue of origin, and it is thus surprising to observe a low frequency of TERT promoter mutations in UCs." (PMID 25474136, 2014). "In this study, we show for the first time that subsets of adrenocortical and chromaffin cell tumors carry TERT promoter mutations, thereby proving a genetic event possibly associated with the upregulation of TERT gene expression in these tumor entities." (PMID 24803525, 2014). "The TERT promoter/IDH1/2 mutational profiles of each tumor type can be used in several aspects of the clinical process including stratification of patients, examination of therapeutic response, and selection of treatment, among others." (PMID 24722048, 2014). "TERT promoter mutations were examined across the strata of age and tumor grade, and were found to be associated with poor OS in all subgroups." (PMID 24937153, 2014). "In this study, we establish that the TERT promoter mutation C228T is a recurrent event for this tumor entity, with a frequency of 12% in this cohort." (PMID 24803525, 2014). "Of note, the tumor spectrum associated to TERT over-expression was different from that of control mice, irrespective of this fact, the incidence of cancer in TgTERT mice was reduced to similar levels of those of wild-type mice under a control diet." (PMID 23349740, 2013). "Recently, it has been reported that genetic variants at the 5p15.33 locus, which contains the TERT gene (encoding the catalytic subunit of telomerase), are involved in the susceptibility of many tumor types." (PMID 24260099, 2013). "Future larger studies with paired tumor and constitutional DNA should be able to definitively address the role of dipyrimidine mutations in the TERT promoter of BCC and SCC." (PMID 24260374, 2013).
tumor (continued). "The biology of TERT makes it a compelling candidate gene for factors that influence cancer risk and the TERT gene has been recognized as one of the most common tumor markers." (PMID 22221621, 2012). "We did not, however, observe any significant association between TCN and TERT or TINF2 expression in the tumour samples (Spearman rank correlation, R = −0.31, P = 0.36, N = 11; R = −0.05, P = 0.88, N = 11, respectively)." (PMID 22952882, 2012). "It suggested a potential modified effect of TERT-CLPTM1L polymorphisms by tumor origins and the rational of stratified analyses." (PMID 23226346, 2012). "This conclusion is supported by studies showing that MDV harboring a mutated vTR incapable of interaction with TERT (P6.1mut) can still induce tumors in chickens, albeit resulting in a delayed onset of tumor formation." (PMID 22046133, 2011). "Combined discovery and replication analysis: risk estimates for TERT rs7726159 for all races according to tumor behaviour and histological subtypes." (PMID 20628624, 2010). "TERT promoter mutations significantly correlate with older age, larger tumor size, and male sex." (PMID 40363930, 2025). "We therefore hypothesized that a high RAS AF could similarly be associated with a second high-risk mutation, such as a TERT promoter mutation, potentially contributing to more aggressive tumor behavior." (PMID 40940948, 2025). "Additionally, EGFR amplification, TERT promoter mutations, and chromosomal markers such as +7/-10 not only assist in diagnosis but also reveal tumor heterogeneity, providing evidence for targeted therapy." (PMID 41201287, 2025). "In contrast, TERT promoter mutations may be a more favorable target because they appear more consistent throughout tumor progression." (PMID 40489430, 2025). "Integrating these features with patient-specific molecular and genetic profiles (e.g., IDH mutation status, MGMT promoter methylation, EGFR amplification, TERT promoter mutations) allows for non-invasive prediction of tumor biology, prognosis, and potential treatment response." (PMID 41465586, 2025). "Increased neoantigen load associated with TERT mutations may broaden the anti-tumor CD8+ T-cell response." (PMID 39422848, 2025). "High levels of TERT and telomerase activity in cells harboring tumor-promoting mutations and genomic instability confer cellular immortality by preventing cellular replicative senescence and apoptosis induced by telomere erosion, thus promoting tumor formation and progression." (PMID 40227701, 2025). "For cancer types with no or marginal associations for the alleles/haplotypes tested, TERT-related mechanisms might be more heterogeneous and dependent on cell specificity, tumor subtype, timing, and the nature and intensity of environmental exposure." (PMID 39956830, 2025). "Even when the germline phenotype is cancer-related there may be discrepancies in mechanism (e.g., TERT loss of function in the germline versus increased expression somatically in certain tumours)." (PMID 39761285, 2025). "Several tumours have reported the mutation in TERT promotor, altering cell division and survival." (PMID 40307280, 2025). "TERT encodes telomerase, which is known to have a key role in carcinogenesis across tumor types." (PMID 40823170, 2025). "Both tumors are driven by UV-induced mutations in tumor suppressor genes and the TERT promoter." (PMID 40507266, 2025). "Patient 7 had a TERT mutation (c.‐146C>T) both in the primary and relapsed tumor." (PMID 40439002, 2025). "TERT amplification associated independently with tumor-related recurrence and death." (PMID 40272676, 2025). "TERT, which encodes the telomerase reverse transcriptase, promotes telomere lengthening and cellular immortality; its gain-of-function mutations are linked to aggressive tumor behavior and decreased survival in adults." (PMID 41590496, 2025).